VDR (vitamin D receptor)
Diseases named in the same sentence as VDR in open-access papers (continued):
Sharing a sentence is not in itself a finding about the gene and the disease.
chronic obstructive pulmonary disease (8 papers, 2012 to 2025). A chronic and progressive lung disorder characterized by the loss of elasticity of the bronchial tree and the air sacs, destruction of the air sacs wall, thickening of the bronchial wall, and mucous accumulation in the bronchial tree. "This indicates that VDR dysregulation is linked to the pathogenesis of both acute lung injury and chronic obstructive pulmonary disease." (PMID 37627629, 2023). "Dysregulation of vitamin D receptor (VDR) is implicated in chronic obstructive pulmonary disease." (PMID 37627629, 2023). "Genetic variants in the 25-hydroxyvitamin D pathway have been associated with chronic obstructive pulmonary disease (COPD) and many polymorphisms in the VDR gene have been linked with infection." (PMID 22726649, 2012).
endometrial cancer (8 papers, 2017 to 2025). Primary or metastatic malignant neoplasm involving the endometrium (mucous membrane that lines the endometrial cavity). "Previous research examining vitamin D status and VDR expression in relation to other gynecologic diseases has found that high systemic 25(OH)D levels and strong tissue VDR expression are associated with a reduced risk of gynecologic malignancies, including ovarian and endometrial cancer." (PMID 40722678, 2025). "In endometrial cancer, displacement of VDR has been associated with a lower histological grade, indicating a potential prognostic role, which suggests that VDR may function as a useful biomarker to predict prognosis and guide treatment decisions in CESC." (PMID 39268267, 2024). "Furthermore, VDR displacement is associated with a lower histological grade in endometrial carcinoma, suggesting that it may serve as a valuable biomarker for disease prognosis and may guide targeted therapies." (PMID 39268267, 2024). "VDR protein expression and nuclear localization were for the first time established by immunohistochemistry in human endometrial cancer tissue by Yabushita and colleagues (1996)." (PMID 30096760, 2018). "As anticipated, VDR levels in endometrial cancer are significantly higher than in control endometrium." (PMID 29113037, 2017). "We agree that future, adequately powered studies including hyperplasia with atypia and endometrial carcinoma are needed to clarify whether VDR expression changes progressively across normal, benign, and malignant endometrial tissue." (PMID 41394244, 2025). "We then performed the labeling using this protocol on nine different human BC cell lines (MCF-7, T47D, Cama-1, ZR75, SK-Br-3, HCC 3153, HCC1937, MDA-MB-231, and MDA-MB-468) and one endometrial cancer cell line Ishikawa ERneg, to analyze the differences in VDR expression." (PMID 28632174, 2017). "Studies examining the role of VDR in endometrial cancer are sparse." (PMID 29113037, 2017). "Similarly, some immortalized human endometrial cancer cell lines (RL95-2 and Ishikawa lines) but not all of them (AMEC-1 cell line) expressed detectable levels of VDR protein." (PMID 30096760, 2018).
epilepsy (8 papers, 2015 to 2026). A brain disorder characterized by episodes of abnormally increased neuronal discharge resulting in transient episodes of sensory or motor neurological dysfunction, or psychic dysfunction. "Genotype and allele distribution of the VDR polymorphisms among cases and controls and the association with the risk of epilepsy." (PMID 26528998, 2015). "While previous data have linked these SNPs with multiple neurological disorders, the evidence concerning the relationship between VDR polymorphisms and epilepsy remains blank." (PMID 26528998, 2015). "As far as we know, these results firstly underline the importance of VDR polymorphisms for the genetic susceptibility to epilepsy." (PMID 26528998, 2015). "Although the exact mechanism is still unclear, several potential physiological mechanisms have been hypothesized for the epilepsy caused by the functional incapacitation of VDR, as follows." (PMID 27408766, 2016). "Furthermore, the association between VDR polymorphisms with TLE found in this study further adds weight to the theory that VD signaling might be involved in the development of epilepsy." (PMID 26528998, 2015). "In this study, we observed a significant increase in vitamin D receptor (VDR) mRNA level at 6-12 h after seizure onset in four distinct classic epilepsy models." (PMID 41958919, 2026). "Four genes (APOL4, KMT2C, SON, VDR) overlapped a clinical epilepsy panel, supporting the capacity of WGS to recover clinically relevant loci." (PMID 42192833, 2026). "Considering that certain genetic variations of VDR may have regulatory effect on VD signaling and metabolism, it is tempting to hypothesize that the particular polymorphisms of VDR could contribute to the development of epilepsy or subgroups of this condition, notably TLE." (PMID 26528998, 2015). "Patients with MRH benefit from both nonselective lumbosacral VDR and ITBP, although VDR obviates the relative contraindications of ITBP including scoliosis, epilepsy, and low BMI." (PMID 41154126, 2025).
fibrosis (8 papers, 2012 to 2024). the formation of excess fibrous connective tissue in an organ or tissue in a reparative or reactive process. "Fibrosis progression has been associated with variants of Vitamin D receptor (VDR) and ABCB11 (bile salt export pump)." (PMID 23342360, 2012). "In our current study, we aimed to evaluate changes in liver NK cells cytotoxicity due to modulations in VDR in CCl4 fibrosis model following 25(OH) D3 injections." (PMID 32276660, 2020). "In this study, we aimed to evaluate changes in liver NK cells cytotoxicity due to modulations in VDR in CCl4 fibrosis model following 25(OH) D3 injections." (PMID 32276660, 2020). "Notably, the anti-hepatic fibrosis effect of vitamin D is closely related to its receptor, i.e., VDR." (PMID 35043727, 2022). "In conclusion, this study revealed the expression of VDR on HSCs and their ability to proliferate and apoptosis, secreting, and degradation of collagen fibers through the LX-2 cell model and the CCl4-induced fibrosis model of SD rats." (PMID 35043727, 2022).
glomerulosclerosis (8 papers, 2013 to 2023). A hardening of the kidney glomerulus caused by scarring of the blood vessels. "Activation of the VDR suppresses renin, has anti‐fibrotic effects, and decreases glomerulosclerosis." (PMID 33026128, 2020). "Due to glomerular basement membrane thickening and podocyte injury, VDR-KO diabetic mice develop more severe albuminuria and glomerular sclerosis and increased expression of fibronectin (FN) than diabetic wild-type mice." (PMID 32766307, 2020). "The renal tissue study of vitamin D receptor knockout diabetic mice showed that the glomerular basement membrane was significantly thickened and the podocytes were significantly reduced, resulting in more severe glomerulosclerosis and obvious proteinuria." (PMID 36142634, 2022). "Moreover, replacement with pharmacologic doses of vitamin D receptor agonists in animal models of kidney disease consistently show reduced albuminuria, abrogated glomerulosclerosis, and glomerular inflammation." (PMID 24083392, 2013). "Though VDR knock-out diabetic mice have developed severe proteinuria and glomerulosclerosis, this study failed to suggest that the action of vitamin D through its receptor and the incidental renoprotective effects may be off-target effects." (PMID 36142634, 2022).
Glucose intolerance (8 papers, 2012 to 2024). Glucose intolerance (GI) can be defined as dysglycemia that comprises both prediabetes and diabetes. "The findings ofOh and Barrett-Connor suggest that VDR genevariant may be associated with glucose intolerance independentof defective insulin secretion and with IR.Mahmoudi indicated that VDR gene variant mayaffect PCOS development as well as IR in womenwith PCOS." (PMID 24520473, 2013). "Pancreatic cells express the VDR gene and the DBP, and certain polymorphisms in the VDR gene may be linked to glucose intolerance and insulin sensitivity, possibly predisposing individuals to the development of T1D." (PMID 39683465, 2024). "In two different mouse models, loss of PVH VDR results in glucose intolerance in DIO males, but not in DIO females, nor in lean mice from either sex." (PMID 35620386, 2022).
Hypercalciuria (8 papers, 2007 to 2025). "Some genetic studies can be performed, especially when there is family history of stones or hypercalciuria, vitamin D receptor and calcium sensor receptor genes." (PMID 39917537, 2025). "Different monogenic polymorphisms have been proposed as playing a causal role for calcium nephrolithiasis, including the VDR gene, CYP24A1, and SLC34A1; however, the complete pathogenetic pathway of hypercalciuria is yet to be determined." (PMID 34959915, 2021). "In contrast, another group did not provide evidence for VDR overexpression in patients affected by hypercalciuria and urolithiasis." (PMID 29562593, 2018).
Nephropathy (8 papers, 2012 to 2023). A nonspecific term referring to disease or damage of the kidneys. "HIV triggers HIV-associated nephropathy through downregulation of VDR." (PMID 37466438, 2023). "In a mouse model of HIV-associated nephropathy a downregulation of vitamin D receptor in renal tissue was observed, and HIV also in vitro downregulated vitamin D receptor expression in podocytes." (PMID 27429711, 2016). "Other nuclear hormone receptors such as vitamin D receptor (VDR) and peroxisome-proliferator-associated receptors (PPARs) are known to play a role in renal inflammation, oxidative stress, fibrosis and renal lipid deposition and their activation may mitigate nephropathy in diabetic animals." (PMID 26583035, 2015). "The activation of the VDR promoted the reduction in the renal microvasculature disturbances by attenuating the TGF-β1/Smad2/3-dependent and downregulation of Ang-2 and AT1 expression, regulating the Angs/Tie-2 and VEGF/VEGFR2 axes, which presents disturbances in ADR-induced nephropathy in rats." (PMID 36558475, 2022).
oral lichen planus (8 papers, 2015 to 2025). Oral lichen planus is a chronic inflammatory oral condition of unknown aetiology characterized by T-cell-mediated chronic immune response and abnormal epithelial keratinization cycle. "Additionally, specific VDR gene SNVs were linked to oral health outcomes, with an increased risk of oral lichen planus for certain genotypes." (PMID 40356850, 2025). "Our findings reveal that miR‐122 promotes oral keratinocytes apoptosis in oral lichen planus by targeting VDR." (PMID 33656264, 2021). "In sum, our results show that vitamin D/VDR signaling induces miR-27a/b in oral lichen planus." (PMID 31942011, 2020). "Authors assume that induction of apoptosis in VDR+ precancerous lesions (e.g. leukoplakia or oral lichen planus) and tumors by vitamin D could be useful for chemoprevention or may act as sensitizers for apoptosis in the treatment of OSCC." (PMID 25662556, 2015). "Vitamin D receptor (VDR) is reported to regulate excessive oral keratinocytes apoptosis which compromises oral epithelial barrier in oral lichen planus (OLP)." (PMID 33656264, 2021). "Vitamin D receptor (VDR) is involved in multiple immune-mediated disorders including oral lichen planus (OLP)." (PMID 32000758, 2020).
Osteopenia (8 papers, 2011 to 2025). Osteopenia is a term to define bone density that is not normal but also not as low as osteoporosis. "In the case of the second VDR gene variant (rs11568820), the GG genotype was more frequent in women with osteopenia (75.5% vs. 70.1% in the control group)." (PMID 39859195, 2025). "In the second variant rs11568820 of the VDR gene, the GG genotype occurred more frequently in women with osteopenia than in the control group." (PMID 39859195, 2025). "In the case of the rs11568820 polymorphism of the VDR gene, the GG genotype was more common in women with osteopenia compared to controls (75.5% vs. 70.1%)." (PMID 39859195, 2025). "Interestingly enough, the authors of another paper describing a group of 300 healthy Saudi women showed that the patients who carried the GG allele for the VDR gene rs731236 polymorphism demonstrated a higher risk of osteopenia." (PMID 38672272, 2024). "Additionally, the Bsml Vitamin D receptor (VDR) gene has been shown to be linked with the osteopenia that develops in thalassemia." (PMID 25834825, 2015). "In contrast, transplantation of VDR null bone into wild-type mice resulted in increased bone mass and vice versa, transplantation of wild-type bone into VDR null mice developed osteopenia, implying a direct inhibitory role of 1,25(OH)2D3 in osteogenesis." (PMID 21695192, 2011). "VDR gene polymorphisms were previously associated with osteopenia in non-cancer settings." (PMID 30533396, 2018).
parathyroid tumors (8 papers, 2006 to 2022). "In the Basic Research cluster, its hotspots focus on Multiple endocrine neoplasia type 1, Parafibromin Immunostainings of Parathyroid Tumors, MEN1 Mutations and Calcium-Sensing Receptor and Vitamin D Receptor." (PMID 35198447, 2022). "Previous studies have reported downregulation of VDR andCASR mRNA levels in parathyroid tumors as compared with the normal rim." (PMID 26865585, 2016). "VDR was found to be decreased in parathyroid tumors, which may promote parathyroid cell proliferation, set-point for calcium sensing receptor (CaSR), and influence the clinical manifestation of HPT." (PMID 33910638, 2021). "The VDR baT haplotype has been related to enhanced abnormality in the calcium regulation of the parathyroid hormone secretion from adenomatous parathyroid cells of primary human parathyroid tumor." (PMID 16507122, 2006).
rectal cancer (8 papers, 2007 to 2023). A primary or metastatic malignant neoplasm that affects the rectum. "Research on the BsmI and poly-A VDR polymorphism showed significant risk reduction for rectal cancer among individuals with SS or BB genotypes and accompanying low calcium intake." (PMID 24093824, 2013). "In at least one study, Pro12Ala allele interacts with vitamin D receptor (VDR)/bsm/polyA to increase risk of rectal cancer." (PMID 19390629, 2009). "Japanese may be more vulnerable to rectal cancer due to the low prevalence of this protective VDR genotype." (PMID 17622244, 2007).
renal failure (8 papers, 2005 to 2023). "Our study found that VDR gene polymorphism was associated with renal insufficiency of IgAN." (PMID 31218132, 2019). "For example, treatment for 2 weeks with AMG641, a calcimimetic compound more potent than cinacalcet, upregulated the expression of both CaSR and VDR in rats with renal insufficiency to the similar levels of control." (PMID 34787825, 2022). "The 5/6nephrectomized (NX) rats with experimentalchronic renal insufficiency were treated with orwithout paricalcitol, a VDR activator." (PMID 20169119, 2010).
respiratory infections (8 papers, 2015 to 2025). "While this comparison must be interpreted with caution due to its small cohort, it contributes to the literature on VDR variants in respiratory infections." (PMID 41301713, 2025). "In addition, one small study has shown associations between VDR polymorphisms and acute lower respiratory infections in children." (PMID 25849649, 2015). "Respiratory monocytes/macrophages and epithelial cells constitutively express the vitamin D receptor (VDR) thereby protecting against respiratory infections." (PMID 32331343, 2020). "Comparatively, KD patients exhibit higher Vitamin D Receptor (VDR) expression in T cells than children with febrile respiratory infections or healthy individuals, suggesting that overactivated T cells may trigger the release of 25-(OH) D3." (PMID 38919394, 2024). "Numerous studies have demonstrated the role the 1,25(OH)2D-ligated VDR plays in binding to a VDRE in the promoter of the cathelicidin gene to enhance hCAP-18 production, thus suggesting a potential mechanism by which vitamin D may enhance innate immunity to respiratory infections." (PMID 26035247, 2015).
schizophrenia (8 papers, 2015 to 2025). A major psychotic disorder characterized by abnormalities in the perception or expression of reality. "Deficiency of vitamin D exerting its effects through VDR (vitamin D receptor) has been observed in schizophrenia patients." (PMID 31481665, 2019). "One CpG site showed significant colocalization: cg08170519 is located in IGSF9B, a gene involved in GABA neurotransmission/inhibitory synapse development and Vitamin D receptor pathway processes, which have been repeatedly implicated in schizophrenia (Cui, McGrath, Burne, & Eyles, 2021)." (PMID 37469193, 2024). "Other significant pathways have relevance to the regulation of neurogenesis and schizophrenia, including ‘IGF-1 Signalling’ and ‘VDR/RXR Activation’ (vitamin D receptor and retinoid X receptor pathways) (both p < 0.0001)." (PMID 38704390, 2024). "We have also described over-expression of VDR, CYP27B1, and CYP24A1 in peripheral blood of patients with schizophrenia compared with healthy subjects in our previous study." (PMID 35279108, 2022).